SNORD19B (small nucleolar RNA, C/D box 19B)
Gene: Small nucleolar RNA gene on chromosome 3 (52,690,744 to 52,690,827, forward strand). Ensembl gene ENSG00000238862.
Gene Ontology:
Biological process: RNA processing
Cellular component: nucleolus
Homologues: Orthologues: chimpanzee SNORD19B (99% identical), macaque SNORD19B (98% identical), pig SNORD19B (82% identical), rabbit SNORD19B (82% identical), guinea pig SNORD19B (81% identical), rat Snord19b (74% identical), mouse Gm24916 (73% identical).